EPCAM (epithelial cell adhesion molecule)
Diseases named in the same sentence as EPCAM in open-access papers (continued):
Sharing a sentence is not in itself a finding about the gene and the disease.
cancer (continued). "The EpCAM/B-cell lymphoma-2 (Bcl-2) signaling pathway prevents platinum-dependent apoptosis of cancer cells resulting in chemo-resistance; therefore, EpCAM expression is increased in tumors of chemo-resistant patients and correlates with unfavorable outcome." (PMID 35269636, 2022). "As the expression of cancer markers can vary at the cellular level, the quantification of EpCAM density in individual cells can help clinicians monitor the phenotypic evolution of cancer cells." (PMID 35735565, 2022). "In this study, we focused on several DARPin constructs designed to target epithelial cell adhesion molecules (EpCAM), an antigen overexpressed on the cell surface of certain cancer cells." (PMID 36232839, 2022). "Taken together, EpCAM as a cancer cell surface antigen displays an important role in targeted therapies." (PMID 35414783, 2022). "In 2009, catumaxomab—a rat–mouse hybrid bsAb for the CD3 epithelial cell adhesion molecule (EpCAM)—was first approved by the EMA for the treatment of malignant ascites in patients with EpCAM-positive cancer." (PMID 35628495, 2022). "The expression of DKK-1 was higher in isolated EpCAM+ cancer stem cells compared with that in EpCAM− cells." (PMID 35269944, 2022). "Herein, the biomarker expression of both MCF-7 and PC-3 cancer cell lines, with high and low EpCAM expression, respectively, was successfully measured with aptamer-functionalized gold nanostarts." (PMID 35735565, 2022). "Future studies with larger patient population and clinical follow up will contribute more information on the significance of CD45+EpCAM+ cell elevation in cancer patients' PBMCs." (PMID 36147748, 2022). "EpCAM, CK, and vimentin are the most commonly used molecular markers to identify CTCs and have been verified in several cancers." (PMID 35740311, 2022). "The CellSearch system, using EpCAM antibodies, is the gold standard for measuring CTCs in other cancer types; it has been reported to be effective in predicting prognosis and risk of recurrence for gastric cancer." (PMID 35017627, 2022). "EpDT3 is a 19-nt RNA aptamer, which can specifically bind to cancer cells overexpressing the epithelial cell adhesion molecule (EpCAM) on the cell surface and be endocytosed after binding with molecules." (PMID 35684384, 2022). "In this study, WT1 and SMAD4P130L expressions in EpCAM+ cancer cells were found, and the existence of CD8+ T cells, which respond to cancer antigens in MPE samples, was clarified." (PMID 36293034, 2022). "Gene amplification is one of the regulation manners to induce EpCAM expression in human primary cancers, including lung, bladder, cervical, and esophagus." (PMID 36077658, 2022). "The number of Tregs also correlates with the proportion of epithelial cell adhesion molecule (EpCAM)+ cancer-derived epithelial cells in MA, and they increase with stage." (PMID 36142615, 2022). "Subcluster 3 expressed limited epithelial marker of EPCAM but cancer stem cell marker CD44 and NOTCH2." (PMID 35733218, 2022). "EMT-expressing cancer cells showed decreased expression of epithelial cell markers such as E-cadherin and EpCAM, while expression of mesenchymal cell markers such as vimentin and N-cadherin increased." (PMID 35942366, 2022). "EpCAM is overexpressed in various cancers, such as ovarian cancer, CRC, breast cancer, lung cancer, and pancreatic cancer." (PMID 35628495, 2022). "The channel surface was functionalised with EpCAM antibodies to capture EpCAM-positive cancer cell lines, such as MCF-7, SW480, PC-3, and EpCAM-negative 293T cells." (PMID 35448280, 2022). "We found that plasticity, which re-programmed CD44(-) differentiated cancer into CD24(+)CD44(+)EpCAM(+) CICs, was inhibited when JAG1 was neutralized." (PMID 35673567, 2022). "Upon further analysis of the cancer group, we observed significantly higher EpCAM mean fluorescence intensity in early-stage cancer samples (Stage I/II) compared to later stage cancer samples (Stage III/IV), (p = 0.047)." (PMID 35976857, 2022).
cancer (continued). "Since EpCAM is broadly expressed on cancer cells, especially CSCs, EpCAM-targeting aptamers are widely used in cancer treatment." (PMID 36369033, 2022). "Achievements in EpCAM research suggest its participation in cancer stemness, cell proliferation, metabolism, angiogenesis, epithelial-to-mesenchymal transition (EMT), metastasis, chemo/radio-resistance and immunomodulation." (PMID 36369033, 2022). "The linearity data and recovery accuracy of the ApoStream® device confirmed consistent cancer cell recovery performance in both high- and low-EpCAM expressing cancer cell types over a wide range of spiking levels." (PMID 35962400, 2022). "Recently, we reported that BMP9 is a crucial factor inducing the malignant nature of HCC and found that BMP9-ID1 signaling promotes cancer stem cell properties in EpCAM-positive HCC cells by activating Wnt/β-catenin signaling." (PMID 35163396, 2022). "Doing so, they managed to capture cancer cells as a function of EpCAM expression by studying their trapping location." (PMID 35216097, 2022). "We observed a significant increase in the percentages of probe H5+ cells within the EpCAM + population in cancer tissue across all patients, indicative of the cytotoxic activity of CD8+ T cells against lung epithelial cells in tumors." (PMID 35501326, 2022). "Given its versatile functions in cancer biology, EpCAM is considered as an attractive target for translational medicine." (PMID 36369033, 2022). "The impacts on the biology of cancers and the up-to-date clinical applications of EpCAM are also introduced and summarized, aiming to shed light on the translational prospects of EpCAM." (PMID 36369033, 2022). "Given the expression characteristics, EpCAM is utilized as a standard molecular marker for identification and isolation of cancer cells from blood, bone marrow, lymph nodes, and biopsy samples." (PMID 36077658, 2022). "With EPCAM, there were positive correlations with 14 cancer types (as expected) and negatively correlated with one cancer type." (PMID 36230521, 2022). "The authors demonstrated that the anti‐EpCAM‐biotin‐Ppy platform was capable of selective capture of cancer cells from blood and efficient release of them following the application of a nondestructive negative potential." (PMID 37324582, 2022). "The epithelial cell subpopulation from the cancer group expressed also higher levels of EpCAM, though equal levels of panCK." (PMID 35976857, 2022). "Epithelial cell adhesion molecule (EpCAM) functions not only in physiological processes but also participates in the development and progression of cancer." (PMID 36369033, 2022). "Epithelial cell adhesion molecule (EpCAM)+ cancer cells (PD-L1− or T cell immunoglobulin mucin-3, TIM-3−), both PD-1 or TIM-3 positive CD8+ T cells, and CD14+CD68+CD163+TIM-3+ macrophages increased from the MPE1st to MPE2nd." (PMID 36293034, 2022). "After 5 days, FACS-sorted EpCAM-positive cancer cells from CIPCOs were analyzed by quantitative RT-PCR." (PMID 35565206, 2022). "We first optimized the PLA conditions with EpCAM-positive cancer cell lines, which model the epithelial phenotype of CTCs, seeded on glass coverslips." (PMID 35454795, 2022). "With IgG isotype nanoparticles (control), between 83% and 91.4% of the cancer cells remained in the blood samples, with anti-EpCAM nanoparticles only 0.8 to 1.5% remained." (PMID 35890293, 2022). "It is conceivable that targeting c-Met, along with other aberrant proto-oncogenes, can modulate c-Myc expression and cell survival in EpCAM-positive and overexpressed c-Met-resistant cancer cells." (PMID 35986321, 2022). "Other preclinical studies have demonstrated efficacy of bispecific antibodies targeting VEGF and EpCAM on HCC cancer cells in mice, providing basis for additional studies in humans." (PMID 35433430, 2022).
cancer (continued). "Downregulation of GSK-3β, a Wnt/β-catenin inhibitor, increased the EpCAM+ subpopulation of cancer cells." (PMID 36369033, 2022). "We selected EpCAM to serve as a target antigen because EpCAM is a pancancer marker that is highly expressed on cancer cells and has been shown to be a marker for cancer-initiating stem cells." (PMID 36451817, 2022). "We also noticed the cancer stem cell gene signature SOX2 and EPCAM was clustered in the brown module, moreover, cancer stem cell has been reported exhibiting resistance to immunotherapy." (PMID 35768785, 2022). "The same glutathione linker is also used to functionalize CNTs with transferrin or an anti-epithelial cell adhesion molecule antibody (anti-EpCAM mAb) as a targeting vector for cancer cells." (PMID 35740342, 2022). "Cancer cell markers, determined by epithelial cell adhesion molecule, and EpCAM+ cells were observed in 0.60% and 1.28% of whole cells in the first (MPE1st) and second (MPE2nd) experiments (obtained two months after MPE1st), respectively." (PMID 36293034, 2022). "The epithelial cell adhesion molecule (EpCAM) is a cell surface glycoprotein, which is widely expressed on normal and cancer cells." (PMID 35735360, 2022). "EpCAM is expressed frequently and at high levels in various cancers but at low levels in normal cells." (PMID 36559056, 2022). "Several lines of evidence suggest that EpCAM and c-Met as signal transducers contribute to Wnt downstream effectors to initiate and develop cancer." (PMID 35986321, 2022). "Catumaxomab was initially approved by the FDA for intra-peritoneal treatment of recurrent symptomatic malignant ascites in patients with EpCAM-positive cancers resistant to conventional chemotherapy." (PMID 36432631, 2022). "Given its versatile functions in cancers, EpCAM participates in multiple steps of cancer progression." (PMID 36369033, 2022). "For example, our previous studies show that these two cell lines have different surface expression levels of drug efflux pumps (MDR1 and ABCG2), as well as different levels of cancer stem cell surface markers (EpCAM and CD133)." (PMID 36358973, 2022). "Several clinical trials have demonstrated promising outcomes, and Catumaxomab has been approved by the European Union for the treatment of patients with malignant ascites in EpCAM-positive carcinomas." (PMID 35735360, 2022). "The majority of EpCAM+EGFR+ events detected in blood samples of cancer patients were doublets of PBMCs, red blood cells or a combination thereof." (PMID 36613466, 2022). "Olaparib treatment not only inhibited the development of mammospheroids but also downregulated the expression levels of cancer stemness markers, such as EpCAM, Nanog and Sox2." (PMID 36109724, 2022). "In HCC, miR-30e-3p was found to bind the 3′UTR of EpCAM mRNA to downregulate its expression, thus inhibiting the stemness and chemoresistance of cancer cells." (PMID 36369033, 2022). "The epithelial cell adhesion molecule (EpCAM) is considered an essential proliferation signature in cancer." (PMID 36428553, 2022). "Cancer-specific biomarkers such as Epithelial Cell Adhesion Molecule (EpCAM), N-cadherin, and Human Epidermal Growth Factor Receptor 2 (HER2) are overexpressed on the CTCs’ surface." (PMID 35323454, 2022). "Cell surface expression level of EpCAM on our panel of cancer cells was tested using flow cytometry." (PMID 35281893, 2022). "Epithelial cell adhesion molecule (EpCAM) was often used to detect cancer cells in the blood because it mediates contact with homotype cells in epithelial tissue." (PMID 35252012, 2022). "Two phase II studies are currently recruiting patients with relapsed or refractory liver (NCT02729493) and stomach (NCT02725125) cancers to evaluate the efficacy and safety of EpCAM-targeted CAR-T cells." (PMID 35207472, 2022).
cancer (continued). "EPCAM expression is observed in epithelial cells and in cancer cells at early stages of the epithelial to mesenchymal transition (EMT)." (PMID 36286037, 2022). "Cancer cells, which are labelled with anti-EpCAM magnetic nanoparticles, entering the valley, will get captured." (PMID 35216097, 2022). "We characterized each process step with two different carcinoma cell lines demonstrating up to 87 % enrichment (n = 10) with EpCAM coupled immunomagnetic beads, 73 % optical detection and dispensing efficiency (n = 5)." (PMID 35573135, 2022). "Epithelial cell adhesion molecule (EpCAM) is a glycosylated cell surface protein overexpressed in various epithelial carcinomas, including breast cancer." (PMID 35414783, 2022). "In contrast to low expression in normal epithelium, EpCAM is frequently overexpressed in various carcinomas, which correlates with poor prognosis." (PMID 36546899, 2022). "Metastatic CSCs overexpress EpCAM antigen, and the administration of EpCAM-CAR NK-92 cell-coexpressing IL-15 has been shown to induce CAR NK cells proliferation with high selective activity against EpCAM-positive carcinoma cells in vivo." (PMID 35395787, 2022). "EpCAM is overexpressed on the basolateral in the epithelial malignancies’ surface of all human carcinomas of various origins." (PMID 35986321, 2022). "The epithelial cell adhesion molecule (EpCAM) is a stem cell and carcinoma antigen, which mediates cellular adhesion and proliferative signaling by the proteolytic cleavage." (PMID 36546899, 2022). "It is based on the use of antibodies against the transmembrane glycoprotein epithelial cell adhesion molecule (EpCAM), which is highly expressed in proliferating carcinomas." (PMID 35806478, 2022). "Epithelial cell adhesion molecule (EpCAM) is a transmembrane glycoprotein expressed during embryonic development and is overexpressed in many epithelial carcinomas, especially CRC." (PMID 35053365, 2022). "Positive selection of CTCs that highly express epithelial cell adhesion molecule (EpCAM) marker is commonly used to isolate CTCs from proliferating carcinomas." (PMID 35884454, 2022). "Current detection methods of CTCs rely on specific surface antigens, namely the transmembrane glycoprotein epithelial cell adhesion molecule (EpCAM) that is highly expressed in carcinomas." (PMID 36425564, 2022). "CD47 showed the next highest expression among cancer cell lines, while the remaining antigens had relatively similar levels of expression, with the exception of EPCAM having a considerable level of expression in Panc02." (PMID 33690223, 2021). "First, relative EpCAM expression levels of four cancer cell lines (SkBr3, HT‐29, HepG2, and T24) were determined using immunofluorescence labeling." (PMID 33301640, 2021). "Due to EpCAM exclusive overexpression in epithelial-derived neoplasms, it can be considered as a suitable target for many solid tumors and cancer stem cells." (PMID 33543415, 2021). "In order to demonstrate that the cells are still viable even before and after the anti-EpCAM antibody-immobilized onto hydrogel, we checked the viability of captured cancer cells." (PMID 34577771, 2021). "Membrane EpCAM is cleaved in cancers and its intracellular domain (EpICD) is transported into the nucleus and binds β-catenin, FHL2, and LEF1." (PMID 34209658, 2021). "On the other hand, JMJD3 plays a role in the histone promotor demethylation of the epithelial cell adhesion molecule (EpCAM) gene playing a role in the proliferative process in some of cancers and which is overexpressed in CRCs." (PMID 33478063, 2021). "The selection of EpCAM as a candidate for a targeted therapy originates from its uniform cell surface distribution on cancer cells which is different from the basolateral localization of EpCAM in normal cells." (PMID 34943898, 2021). "Our expanding knowledge of EpCAM’s role in EMT has provided important pathological markers for cancer patients and is revealing potential therapeutic opportunities." (PMID 34209658, 2021).